ANGPT2 (angiopoietin 2)
Diseases named in the same sentence as ANGPT2 in open-access papers (continued):
Sharing a sentence is not in itself a finding about the gene and the disease.
preeclampsia (5 papers, 2018 to 2025). Preeclampsia is a hypertensive disorder of pregnancy that is characterized by new-onset hypertension with proteinuria presenting after 20 weeks of gestation, and depending on mild or severe forms may initially present with severe headache, visual disturbances, and hyperreflexia. "Angiopoietin-2 is a known biomarker for preeclampsia with the placental expression of angiopoietin-2 found to be significantly increased in preeclamptic patients." (PMID 41286963, 2025).
rheumatoid arthritis (5 papers, 2020 to 2024). A chronic, systemic autoimmune disorder characterized by inflammation in the synovial membranes and articular surfaces. "Moreover, an angiopoietin 2 (ANGPT2) rs3020221 polymorphism was found to influence both CRP and ESR levels in rheumatoid arthritis patients." (PMID 37238156, 2023). "Another study also stated that angiopoietin-2 may be used as a potential biomarker in SLE, since this marker seemed to have potential to differentiate patients with SLE from those with rheumatoid arthritis, osteoarthritis, gout, Sjögren’s syndrome and ankylosing spondylitis." (PMID 39242108, 2024). "Ex-vivo studies, conducted on microvascular endothelial cells and rheumatoid arthritis (RA) explants of whole synovial tissue have shown that TLR2 induces angiogenic tube formation and ANGPT2 expression." (PMID 35877427, 2022).
vascular malformation (5 papers, 2019 to 2026). A non-neoplastic disorder that is the result of defects of vascular morphogenesis. "We showed that loss of ANGPT2 leads to region-specific vascular malformations and blood-brain barrier (BBB) dysfunction, resulting in differential permeability to 1 kDa and 70 kDa fluorescent tracers." (PMID 41712285, 2026). "However, it has been puzzling how “a weak agonist” Angpt2 would be able to induce the level of Tie2 activation as observed in the Tie2 GOF causing vascular malformation mutations." (PMID 33495460, 2021). "A knockout mice study also demonstrated that treatment of Angpt2-neutralizing antibody attenuated the defects in vascular malformations, which shows that Angpt2 can be used for treatment and is not only important as a biomarker." (PMID 37533068, 2023). "In ECs, decreased activity of the BMP9/10 signaling leads to over-activation of the pro-angiogenic factors VEGF-A and angiopoietin-2 (ANGPT-2), triggering EC hyperproliferation, as well as alterations in their permeability and migration, ultimately leading to vascular malformations." (PMID 33844116, 2021).
breast tumour (4 papers, 2015 to 2024). "Compared with the reference, the T-T-C-A-T ANGPT2 haplotype significantly increased the risk for developing a malignant breast neoplasm by 1.385-fold (95% CI: 1.025–1.871; p < 0.05)." (PMID 36008514, 2022). "It is therefore important and appropriate to investigate the impacts of ANGPT2 genetic variants upon the risk of malignant breast neoplasms among women of Chinese Han ethnicity." (PMID 36008514, 2022). "We also found that the T-T-C-A-T ANGPT2 haplotype significantly increased the risk for developing a malignant breast neoplasm by 1.385-fold (95% CI: 1.025–1.871; p < 0.05)." (PMID 36008514, 2022). "When we analyzed the contributions of different haplotype combinations of the five ANGPT2 variants investigated in this study upon the risk of a malignant breast neoplasm, we found that the TTCAT haplotype increased the risk." (PMID 36008514, 2022). "We further explored the haplotypes to evaluate the combined effects of the ANGPT2 polymorphisms on malignant breast neoplasm susceptibility." (PMID 36008514, 2022). "We explored the effects of ANGPT2 SNPs on the susceptibility for a malignant breast neoplasm in a Chinese Han population." (PMID 36008514, 2022). "It is possible that the ANGPT2 TTCAT haplotype is in LD with other functional polymorphisms that increase the susceptibility for a malignant breast neoplasm." (PMID 36008514, 2022). "In conclusion, our systematic genotyping results demonstrate an association between ANGPT2 gene variants and susceptibility for a malignant breast neoplasm and its progression among Chinese Han women." (PMID 36008514, 2022). "Our study is the first to document a correlation between ANGPT2 polymorphisms and the development and progression of a malignant breast neoplasm in females of Chinese Han ethnicity." (PMID 36008514, 2022). "The main strength of our study is its systematic analysis of ANGPT2 SNPs and susceptibility to malignant breast neoplasms in our study population." (PMID 36008514, 2022). "It sought to determine whether Chinese Han women with ANGPT2 SNPs are susceptible to developing a malignant breast neoplasm and whether these SNPs correlate with clinical disease status." (PMID 36008514, 2022). "Additionally, oestrogen depletion triggered oestrogen receptor (ER)-positive breast tumour cell awakening from dormancy by activating angiopoietin-2 (ANGPT2) signalling in the bone marrow niche." (PMID 36307871, 2022). "Based on blood samples from 539 healthy, cancer-free women and 464 women with malignant breast neoplasms, we found no significant between-group distribution frequencies for any of the five ANGPT2 SNPs." (PMID 36008514, 2022).
depression (4 papers, 2016 to 2024). "Moreover, we found that downregulated genes in prefrontal cortex of CUMS group such as Sfrp5 and Angpt2, which were correlated with depression, were reversed by the probiotics." (PMID 38855745, 2024).
endotoxemia (4 papers, 2009 to 2025). "Finally, the presence or absence of ODN did not change endotoxemia outcomes when either ANGPT2 fragment was overexpressed." (PMID 40029709, 2025).
hypercoagulability (4 papers, 2021 to 2026). "We find that the ANGPT2 levels correlate with several markers of hypercoagulation and mortality." (PMID 35740360, 2022).
Hyperglycemia (4 papers, 2012 to 2026). An increased concentration of glucose in the blood. "Therefore, the hyperglycemia- as well as the NDPK-B deficiency-induced vascular damage was prevented in mice haplodeficient for the Ang2 encoding Angpt2 gene." (PMID 32466219, 2020). "RESULTS: Hyperglycemia and the accumulation of advanced glycation end products upregulate angiogenic growth factors and inflammatory cytokines, notably vascular endothelial growth factor (VEGF) and angiopoietin-2." (PMID 41851808, 2026).
metastatic colorectal cancer (4 papers, 2013 to 2023). "It has been reported that patients with advanced metastatic colorectal cancer had high serum levels of ANGPT2, and Bevacizumab therapy reduced these levels, suggesting that it may play a role in modulating its effect on VEGF levels." (PMID 38313162, 2023).
oral cancer (4 papers, 2016 to 2022). "An additional gene at this locus, ANGPT2, is also associated with oral cancer, and upregulated in response to P. gingivalis, a periodontal pathogen." (PMID 31533690, 2019). "CCL4 treatment of oral cancer cells upregulated Angpt2 expression and stimulated mitogen-activated protein kinase kinase (MEK), extracellular signal-regulated kinase 1/2 (ERK), and signal transducer and activator of transcription 3 (STAT3) phosphorylation." (PMID 35884919, 2022). ", demonstrated that NaB inhibited pro-lymphangiogenic factors (e.g. VEGF-C and angiopoietin-2) in the oral cancer cell line HSC-3." (PMID 27716272, 2016). "Transfection of oral cancer cells with MEK, ERK, and STAT3 inhibitors and their small interfering RNAs inhibited CCL4-induced promotion of Angpt2 expression and angiogenesis." (PMID 35884919, 2022).
pancreatic neuroendocrine tumor (4 papers, 2018 to 2025). Pancreatic endocrine tumor, also known as pancreatic neuroendocrine tumor (PNET), describes a group of endocrine tumors originating in the pancreas that are usually indolent and benign, but may have the potential to be malignant. "Blocking ANGPT2 helps prevent pancreatic neuroendocrine tumors from spreading to the liver by increasing T-cell infiltration and stimulating the immune response." (PMID 40061897, 2025). "Combined blockade of ANGPT2 and VEGFA with a bispecific antibody (A2V) showed superior therapeutic efficacy compared with single agents in genetically engineered and transplanted tumor models, including metastatic breast cancer, pancreatic neuroendocrine tumors, and melanoma models." (PMID 38193080, 2023).
psoriasis (4 papers, 2020 to 2025). An autoimmune condition characterized by red, well-delineated plaques with silvery scales that are usually on the extensor surfaces and scalp. "Psoriasis development was associated with an increase in the level of angiopoietin-2 and HGF by 25%, of PDGF by 80%, of TNFα and VEGF twice, and of FGF three times as compared to healthy cells." (PMID 34691360, 2021). "The Angiopoietin 2 and Tie2 interaction has been shown to play a role in psoriasis." (PMID 41562711, 2025). "Successful treatment of psoriasis results in downregulation of Angiopoietin 2, suggesting that Angiopoietin 2 might be an interesting target for antipsoriatic therapies." (PMID 41562711, 2025).
respiratory failure (4 papers, 2021 to 2026). The significant impairment of gas exchange within the lungs resulting in hypoxia, hypercarbia, or both, to the extent that organ tissue perfusion is severely compromised. "Most of the clinical associations for ANGPT2 have been described in critical patients (shock or respiratory failure)." (PMID 37737266, 2023).
retinal diseases (4 papers, 2021 to 2025). "Angiopoietin-2 (Ang-2) has also been demonstrated to be upregulated in patients with different retinal diseases." (PMID 38233896, 2024). "YOSEMITE and RHINE were the first registrational trials in retinal disease to incorporate an objective PTI regimen, allowing for up to every-16-week adjustable dosing with a dual angiopoietin-2 and VEGF-A inhibitor, faricimab 6.0 mg, for treatment of DME." (PMID 36246184, 2021). "In vivo data suggest that anti-VEGF agents currently used for the treatment of retinal diseases could provide beneficial effects beyond direct binding of VEGF, including suppression of ANG2 protein and ANGPT2 mRNA." (PMID 37191621, 2023).
acute coronary syndrome (3 papers, 2020 to 2025). Signs and symptoms related to acute ischemia of the myocardium secondary to coronary artery disease. "Elevated ANGPT2 levels have been found in patients with acute coronary syndrome, hypertension, congestive heart failure and congenital heart failure." (PMID 32575548, 2020).
Astrocytomas (3 papers, 2010 to 2024). "EGF-associated pathways and angiopoietin 2 have been used as a point of differentiation between grade IV astrocytoma, i.e., glioblastoma multiform from lower-grade astrocytoma." (PMID 39796008, 2024).
autoimmune disease (3 papers, 2017 to 2022). A disorder resulting from loss of function or tissue destruction of an organ or multiple organs, arising from humoral or cellular immune responses of the individual to their own tissue constituents. "Moreover, angiopoietin 2 positively regulates angiogenesis in autoimmune diseases." (PMID 28827845, 2017).
cardiac hypertrophy (3 papers, 2016 to 2023). "Although we found the significant association of Angpt2 with cardiac hypertrophy and correlation between Angpt1 and LAD, the p-values for trend seemed to be low." (PMID 27991547, 2016). "A study using angiopoietin 2-induced cardiac hypertrophy mice noted that FGF21 treatment increased SIRT1 deacetylation activity, promoted AMPK phosphorylation, and reduced cardiac hypertrophy in a SIRT1-dependent pathway." (PMID 37416922, 2023). "Angpt2, impaired renal function, and inflammation might have a synergic effect on cardiac hypertrophy." (PMID 27991547, 2016).
Cerebral ischemia (3 papers, 2015 to 2021). Restriction of arterial blood supply to the brain associated with insufficient oxygenation to support the metabolic requirements of the tissue. "Changes in Hif-1a expression by the administration of either anti miR-335 or miR-335 mimic in cerebral ischemia were accompanied with the corresponding alteration of the downstream genes Angpt2, Bnip3, Mmp9, Pai1 and Vegfa." (PMID 26030758, 2015). "Since Angpt2, Bnip3, Mmp9, Pai1 and Vegfa genes are also important key players in cerebral ischemia, it is possible that the overall changes in their expression synergistically contribute in bringing about the beneficial effect of miR-335 in reducing the infarct volume." (PMID 26030758, 2015). "The selection of the growth factors evaluated in the present study (angiopoietin-2, VEGF-A, and G-CSF) was performed due to previous pre-clinical models of cerebral ischemia." (PMID 34572453, 2021). "We verified the expression of Angpt2, Bnip3, Mmp9, Pai1 and Vegfa genes since they were reported to be regulated by HIF-1α during cerebral ischemia." (PMID 26030758, 2015).
cognitive decline (3 papers, 2024 to 2025). "Taken together, the elevated levels of angiopoietin-2, Serpin E1, uPAR, and IL-18 may promote chronic inflammation, blood–brain barrier dysfunction, and neuronal damage, contributing to the neuroinflammation and cognitive decline characteristic of SZ." (PMID 39940697, 2025). "CSF levels of PlGF, ANGPT2, and sPDGFRβ were elevated from early‐stage AD, that is, CDR 0.5, and were strongly related to CSF Aβ1‐40, t‐tau, p‐tau, and cognitive decline across multiple domains: CDR, MoCA, MMSE, and ADAS." (PMID 41319164, 2025).
Cognitive impairment (3 papers, 2017 to 2023). Abnormal cognition is characterized by deficits in thinking, reasoning, or remembering. "Finally, probably the most important finding of this study was the detection of altered levels of those biological attributes, for subjects with cognitive impairment, that could have potential as therapeutic targets in AD, namely decreased leptin and increased angiopoietin-2 plasma levels." (PMID 29088293, 2017).
colorectal tumor (3 papers, 2018 to 2024). "Moreover, our study identified a significant association between VEGF-A and ANGPT-2 overexpression, as well as ANGPT-1 downregulation with colorectal tumor metastasis and reduced overall survival." (PMID 38719941, 2024).
cutaneous malignant melanoma (3 papers, 2021 to 2024). "The aim of this study was to investigate angiopoietin-2 (Ang-2/ANGPT2) expression and its relationship with lymphangiogenesis and clinicopathological characteristics in cutaneous malignant melanoma (CMM)." (PMID 37519819, 2023). "ANGPT2 gene expression is significantly higher (P < 0.01) in skin melanoma compared to normal skin, whereas expression of ANGPT1, PDGFA, FGF2, and VEGF‐A is not significantly different." (PMID 34102002, 2021).
endometrial cancer (3 papers, 2014 to 2022). Primary or metastatic malignant neoplasm involving the endometrium (mucous membrane that lines the endometrial cavity). "Similar synergistic effects have also been demonstrated by the simultaneous blockade of Angpt2 and VEGF in mice with endometrial cancer, where combined silencing more effectively reduced tumor size and angiogenesis than the individual targeting of either Angpt2 or VEGF." (PMID 35884919, 2022). "Furthermore, the association between the expression of HIF-1α, increasing level of angiopoietin-1/angiopoietin-2, and enhanced synthesis of IL-8 was documented, also confirming the role of HIF-1α in the angiogenesis of endometrial cancer." (PMID 24745019, 2014).
gastric adenocarcinoma (3 papers, 2022 to 2025). "RT-qPCR results indicated that the mRNA expression levels of four hypoxic endoplasmic reticulum stress-related differential genes—NOX4, ANGPT2, CD36, and TLR2—were correlated with our established prognostic risk model in both gastric adenocarcinoma and adjacent normal tissues." (PMID 40061897, 2025). "Several in vitro studies, including our own observations (manuscript submitted), show that in co-cultures H. pylori induces the expression of ANGPT2, VEGFA and other angiogenesis-related factors in gastric adenocarcinoma cell lines." (PMID 36874142, 2023).
leukemia (3 papers, 2015 to 2020). A malignant (clonal) hematologic disorder, involving hematopoietic stem cells and characterized by the presence of primitive or atypical myeloid or lymphoid cells in the bone marrow and the blood. "In the leukemia mouse model, we did observe increased gene expression of VEGF, HIF-1α and ANGPT-2, which were significantly reduced after HF treatment." (PMID 26099922, 2015).
Liver Disease (3 papers, 2011 to 2022). "The levels of HIF-1α, vascular endothelial growth factor (VEGF), and angiopoietin-2 (Ang-2) expression in the sera of 220 patients with liver disease were quantitatively detected by ELISA." (PMID 22224081, 2011).
metastatic disease (3 papers, 2019 to 2025). "For ANGPT2 SNPs, rs55633437 was associated with extra-hepatic spread; in particular, 64% of patients with at least one copy of the T allele presented with metastatic disease." (PMID 31330833, 2019). "PTN, MK, PVRL4, EPHA2, TFPI-2, hK11, SYND1, ANGPT2 and hK14 were found elevated in the metastatic disease when compared to cancer-free, CPG1 and/or CPG5 groups." (PMID 33288843, 2021). "Additionally, ANGPT2 can regulate lymphatic vessel development, suggesting its crucial role in lymph node metastatic tumors." (PMID 40095604, 2025).
ovarian tumor (3 papers, 2011 to 2020). "Low angiopoietin-2 expression levels in primary ovarian tumors were significantly associated with shorter overall survival (p = 0.015) in the univariate survival analysis." (PMID 33151982, 2020). "We used immunohistochemistry (IHC) to detect the expression of Ets-1, angiopoietin-2 (Ang-2) and maspin in ovarian tumor and analyzed the relationship between the expression of these proteins and the clinical manifestation of ovarian cancer." (PMID 21439064, 2011).
primary lymphedema (3 papers, 2022 to 2024). A congenital condition that results in swelling in the arms or legs, and can occur during adolescence or adulthood. "Angiopoietins (Angs) and their Tie receptors regulate lymphatic vessel development, and mutations of the ANGPT2 gene were recently found in human primary lymphedema." (PMID 35763346, 2022). "Prior studies have identified mutations in piezo-type mechanosensitive ion channel component 1 (PIEZO1), angiopoietin 2 (ANGPT2), and tyrosine kinase with Ig-like and EGF-like domains 1 (TIE1) in patients with primary lymphedema." (PMID 38747287, 2024).
primary open-angle glaucoma (3 papers, 2019 to 2022). "Heterozygous loss of function variants in TEK or its primary ligand ANGPT1 have been linked to PCG in children, and ANGPT1 and ANGPT2 have been associated with primary open-angle glaucoma (POAG) in adults." (PMID 34663817, 2021).
proliferative diabetic retinopathy (3 papers, 2022 to 2025). Advanced retinopathy due to diabetes mellitus characterized by the formation of new vessels in the retina. "Effects of gender and type of diabetes on the levels of PGC-1α, vascular endothelial growth factor (VEGF) and angiopoietin 2 in vitreous samples from patients with proliferative diabetic retinopathy." (PMID 40747314, 2025). "We detected up-regulated levels of VEGF-A (p = 0.001), PIGF (p<0.001), Angiopoietin-1 (p = 0.005), Angiopoietin-2 (p<0.001), IL-1β (p = 0.012), and IL-8 (p = 0.018) in proliferative diabetic retinopathy samples." (PMID 36662891, 2023). "Comparisons of PGC-1α, vascular endothelial growth factor (VEGF) and angiopoietin 2 levels in vitreous samples from patients with proliferative diabetic retinopathy (PDR) and nondiabetic patients with rhegmatogenous retinal detachment (RD)." (PMID 40747314, 2025). "In this context we investigated vitreous protein levels, including placental growth factor (PlGF), angiopoietin-2 (ANG2) and vascular endothelial growth factor (VEGF), in patients with proliferative diabetic retinopathy (PDR) with variable disease severities, and after anti-VEGF pre-treatment." (PMID 36473885, 2022).